FES (FES proto-oncogene, tyrosine kinase)
Description:
Tyrosine-protein kinase that acts downstream of cell surface receptors and plays a role in the regulation of the actin cytoskeleton, microtubule assembly, cell attachment and cell spreading. Plays a role in FCER1 (high affinity immunoglobulin epsilon receptor)-mediated signaling in mast cells. Acts down-stream of the activated FCER1 receptor and the mast/stem cell growth factor receptor KIT. Plays a role in the regulation of mast cell degranulation. Plays a role in the regulation of cell differentiation and promotes neurite outgrowth in response to NGF signaling. Plays a role in cell scattering and cell migration in response to HGF-induced activation of EZR. Phosphorylates BCR and down-regulates BCR kinase activity. Phosphorylates HCLS1/HS1, PECAM1, STAT3 and TRIM28.
Synonyms: FPS
Tractability: Small molecule: a structure with a bound ligand is known; a high-quality ligand is known; it has a binding pocket of medium quality; it belongs to a druggable protein family. Antibody: UniProt places it where antibodies can reach, with medium confidence; its Gene Ontology location is reachable by antibodies, with medium confidence. PROTAC: ubiquitination databases record sites on it; its protein half-life has been measured; a small molecule that binds it is known.
Target class: Kinase; Protein Kinase; Enzyme; Tyrosine protein kinase Fer family; TK protein kinase group
Gene: Protein-coding gene on chromosome 15 (90,883,695 to 90,896,213, forward strand). Ensembl gene ENSG00000182511.
Subcellular location: Cytoplasm, cytosol; Cytoplasm, cytoskeleton; Cell membrane; Cytoplasmic vesicle; Golgi apparatus; Cell junction, focal adhesion
Subcellular location (Human Protein Atlas): Cytosol; Nucleoplasm; Vesicles
Pathways (Reactome):
Developmental Biology: CRMPs in Sema3A signaling; SEMA3A-Plexin repulsion signaling by inhibiting Integrin adhesion; Sema3A PAK dependent Axon repulsion
Signal Transduction: Signaling by SCF-KIT
Gene Ontology:
Molecular function: immunoglobulin receptor binding; non-membrane spanning protein tyrosine kinase activity; phosphatidylinositol binding; protein binding; protein tyrosine kinase activity; ATP binding; microtubule binding; protein kinase activity
Biological process: cellular response to vitamin D; peptidyl-tyrosine phosphorylation; positive regulation of microtubule polymerization; positive regulation of monocyte differentiation; positive regulation of myeloid cell differentiation; positive regulation of neuron projection development; protein autophosphorylation; regulation of cell adhesion; regulation of cell differentiation; regulation of cell motility; regulation of cell population proliferation; regulation of cell shape; regulation of mast cell degranulation; cell adhesion; chemotaxis; regulation of vesicle-mediated transport; cardiac muscle cell proliferation; myoblast proliferation; positive regulation of cytoskeleton organization; positive regulation of protein polymerization; positive regulation of supramolecular fiber organization
Cellular component: cytoplasm; cytoplasmic side of plasma membrane; cytoplasmic vesicle; focal adhesion; microtubule cytoskeleton; cytosol; plasma membrane; cytoskeleton; Golgi apparatus
Genetic constraint (gnomAD): Loss-of-function variants: 83 observed, 103.65 expected, observed/expected ratio (o/e) 0.8, 90% interval 0.67 to 0.96. The upper end of that interval is the gene's LOEUF score, 0.96, which puts it in group 4 of 6, group 1 being the genes least tolerant of losing a copy. Missense variants: 943 observed, 1,046.6 expected, observed/expected ratio (o/e) 0.9, 90% interval 0.85 to 0.95. Synonymous variants: 458 observed, 425.8 expected, observed/expected ratio (o/e) 1.08, 90% interval 1 to 1.16.
Cancer hallmarks: angiogenesis (promotes); suppression of growth (promotes); escaping immune response to cancer (suppresses); invasion and metastasis (suppresses); proliferative signalling (promotes); tumour promoting inflammation (suppresses); escaping programmed cell death
Homologues: Orthologues: chimpanzee FES (99% identical), macaque FES (99% identical), dog FES (94% identical), pig FES (94% identical), rat Fes (91% identical), mouse Fes (91% identical), rabbit FES (90% identical), tropical clawed frog fes (66% identical), zebrafish fes (57% identical), guinea pig Fes (11% identical). Paralogues in human: FER (51% identical), ABL2 (21% identical), TEC (21% identical), FYN (21% identical), SRC (21% identical), ABL1 (21% identical), LCK (21% identical), YES1 (20% identical), ITK (20% identical), MATK (20% identical), FGR (20% identical), LYN (20% identical), and 20 more.
Diseases named in the same sentence as FES in open-access papers:
FES is named in the same sentence as 63 diseases in open-access papers, as found by Europe PMC text mining. Sharing a sentence is not in itself a finding about the gene and the disease. The quoted sentences say what the papers report.
atherosclerosis (5 papers, 2017 to 2026). A disease characterized by the build-up of fatty material and calcium deposition in the arterial wall resulting in partial or complete occlusion of the arterial lumen. "Further functional experiments focusing on FES, a pleiotropic gene for both coronary artery disease and hypertension, show that it modulates the expression of genes involved in vascular remodeling and that Fes knockout in mice promotes atherosclerosis as well as raises blood pressure." (PMID 41644529, 2026). "We used the endothelial marker gene CDH5 to identify a cluster of endothelial cells and confirmed that these cells express DHX38, MAT2A, CCDC92, FES and FURIN, prompting future efforts to dissect the role of these genes in this cell type in atherosclerosis." (PMID 36928188, 2023).
Hypertension (4 papers, 2015 to 2026). The presence of chronic increased pressure in the systemic arterial system. "Two other CpG sites, cg09397246 and cg26405020, were located near the transcription start site of FES (FES proto-oncogene, tyrosine kinase), which has been identified by GWAS to be associated with blood pressure and hypertension." (PMID 26015811, 2015). "Increased FES expression colocalised with increased birth weight, increased ovarian cancer risk and decreased blood pressure along with decreased risk of hypertension and other related cardiovascular events and increased FURIN colocalised with decreased birth weight and increased angina risk." (PMID 33417599, 2021).
ovarian carcinoma (3 papers, 2018 to 2022). A malignant neoplasm originating from the surface ovarian epithelium. "In contrast, FES, the only other family member of FER, was undetectable at mRNA level in ovarian cancer cell lines." (PMID 29396402, 2018). "Interestingly, compared to lysates from myeloid leukemia cell HL-60, we detected no FES expression in ovarian cancer cell lines used in this study." (PMID 35550247, 2022).
pancreatic cancer (3 papers, 2021 to 2023). "To determine the FES kinase’s involvement in liver metastasis formation, we implanted KPC pancreatic cancer cells in healthy FES null mice and their WT littermates." (PMID 36969004, 2023). "To further explore the FES kinase and its role in metastatic pancreatic cancer, we used a FES KO mouse model." (PMID 36969004, 2023). "We also isolated bone marrow neutrophils from the KPC mouse model (KrasLSL-G12D/+;Trp53LSL-R172H/+;Pdx1–Cre) with pancreatic tumors and demonstrated that FES was among the group of kinases with significant increased activity compared to neutrophils from tumor-free control mice." (PMID 34099731, 2021).
breast carcinoma (2 papers, 2020 to 2022). "Moreover, a genome-wide association study (GWAS) of breast cancer declared identification of 65 novel loci associated remarkably with a high risk of breast cancer at P < 5 × 10− 8 such as FES, MAP 3 K11, CLK2, GRK7, USP25, DFFA, PKP1, and ZKSCAN3." (PMID 35650591, 2022). "In addition, the methylation level of FES is positively related with tumor stage in breast cancer." (PMID 32256211, 2020).
colon cancer (2 papers, 2018 to 2025). "Additionally, CNV analysis indicated a significant increase in the proportion of CNVs for CHRNA4 and USP42 in colon cancer, while an increase in CNVs for FURIN and FES was noted in rectal cancer." (PMID 40426913, 2025). "On the other hand, kinase-inactivating mutations in the FES gene have been detected in colorectal cancer cells, and low or absent FES expression has been reported in colon cancer specimens compared with matched normal tissues." (PMID 28952025, 2018).
depression (2 papers, 2022 to 2025). "TWAS analysis identified three significant tissue–gene pairs shared between depression and stroke, including TMEM106B in the transverse colon, FES in the heart atrial appendage, and FES in the stomach, which were also shared between depression and ischemic stroke." (PMID 40949012, 2025).
lung carcinoma (2 papers, 2016 to 2021). "The results showed that CCNE1, E2F1, ARHGAP11A, RUNX1T1 and FES were significantly associated with patient survival in lung cancer (n = 1925)." (PMID 33613291, 2021). "For example, mutation/amplification of EGFR in lung cancer cell lines was associated with an increased dependency upon FES (p = 3 × 10−2), previously identified as an EGFR binding partner." (PMID 26947069, 2016).
Obesity (2 papers, 2021 to 2022). Accumulation of substantial excess body fat. "The GTEx track indicates FURIN has the highest median expression in the liver, followed by the pancreas (organs directly relevant to T2D and obesity pathogenesis), whereas FES has the highest median expression in the spleen followed by the lungs." (PMID 35884374, 2022). "Additionally, other causal genes are highly expressed or known to act in human brain function (i.e., NEGR1, GNPDA2, CYP46A1, DGKH) and various carcinomas (i.e., PMAIP1, HORMAD1, FES, BCAS3), indicating the potential role of metabolic dysregulation in the pathogenesis of obesity and cardiac events." (PMID 33910581, 2021).
sarcoma (2 papers, 2013 to 2020). A usually aggressive malignant neoplasm of the soft tissue or bone. "FES was initially identified as an oncogene from the tumor-causing feline sarcoma retrovirus." (PMID 32256211, 2020). "For example, the FES gene (“Feline sarcoma oncogene”) in humans has no known role in sarcoma." (PMID 23951102, 2013).
Sepsis (2 papers, 2023 to 2025). Sepsis is defined as life-threatening organ dysfunction caused by a dysregulated host response to infection. "This study will seek to determine whether the RNA expression levels of FES are associated with the incidence, severity, and outcome of sepsis using bioinformatic analysis." (PMID 37122758, 2023). "Furthermore, we aim to determine whether clinical sepsis outcomes are correlated with single nucleotide polymorphisms (SNPs) associated with differential FES expression." (PMID 37122758, 2023). "We expect that FES expression levels on microarray analysis can be used alone or in combination with other genetic features as a biomarker to determine the presence, stage, severity, and outcome of sepsis." (PMID 37122758, 2023). "We hypothesize that FES expression is related to outcomes in in vivo and in vitro models of sepsis, as well as in clinical populations of patients with sepsis." (PMID 37122758, 2023). "We expect that FES will be upregulated in early-stage and downregulated in late-stage sepsis." (PMID 37122758, 2023). "This lends itself to identifying FES as a treatable trait, where, depending on the timing of intervention and the levels of FES expression or activity, may result in a different approach to treating a patient’s sepsis (upregulating FES expression or inhibiting FES activity)." (PMID 37122758, 2023). "Irrespective of the timing of treatment, we do not expect either lorlatinib or decitabine to affect sepsis severity in FES-/- mice (as there is no FES present to be regulated by either of these drugs)." (PMID 37122758, 2023). "Additionally, if FES expression plays no role in sepsis severity, it will allow us to rule out a potential regulator heavily involved in many aspects of sepsis, which will help to narrow in on true regulators of sepsis severity and outcomes." (PMID 37122758, 2023). "Furthermore, FES knockout (FES-/-) mice demonstrate dysregulation of signal transducer and activator of transcription 3 (STAT3), which plays a vital role in the pathophysiology of sepsis by initiating endothelial dysfunction, vasoplegia, coagulopathy, and multi-organ failure." (PMID 37122758, 2023).
bladder cancer (1 paper, 2018). "Our results identify FES as a potential therapeutic target and a useful prognostic factor for patients with high-grade bladder cancer." (PMID 28952025, 2018). "In conclusion, the pathological and prognostic significance of FES expression depended on tumor grade in patients with bladder cancer." (PMID 28952025, 2018). "The pathological and prognostic significance of FES expression was assessed in patients with bladder cancer, with particular attention to the effect of cancer grade on the relationship between FES levels and pathological characteristics." (PMID 28952025, 2018). "In contrast, although FES immunostaining was often observed in bladder cancer cells, strong expression was only occasionally evident." (PMID 28952025, 2018). "These facts indicate a possibility that unknown co-factors and/or regulators of FES activity affect cell proliferation and invasion in only high-grade bladder cancer." (PMID 28952025, 2018). "In short, loss of cell contact- and adherence junction-associated signaling due to increased malignancy may alter the pathological roles of FES in bladder cancer." (PMID 28952025, 2018). "That increased FES expression was a significant negative prognostic factor for metastasis after radical surgery for patients with high- but not low-grade bladder cancer was a key result of the present study." (PMID 28952025, 2018).
conjunctivitis (1 paper, 2023). Inflammation of the conjunctiva of the eye. "characterized a FES KO mouse in a 129X1/SvJ background with notable low-penetrance defects such as embryonic lethality, cardiovascular defects, runting, skin lesions and conjunctivitis." (PMID 36969004, 2023).
coronary artery disease (1 paper, 2020). "For instance, genetically determined expression of FES was strongly associated with coronary artery disease (per 1 SD OR: 0.90, 95% CI: 0.88–0.92, Pcausal = 1.09 × 10−15), which is consistent with the genetic signal in GWAS by the tag SNP rs17514846 (PGWAS = 9.85 × 10−27) at the FURIN/FES locus." (PMID 32358504, 2020).
diabetes (1 paper, 2020). "The findings that expression of LPR4 and FES is not affected by diabetes status and low expressed in human islets indicate that those genes might not be potential important players in β-cell function." (PMID 32340285, 2020). "Expression of ASAH1, FES, and LRP4 was not affected by diabetes status." (PMID 32340285, 2020).
E. coli infection (1 paper, 2020). "Taken together, these results indicate that FES activity is required for the activation of this signaling pathway in HL-60 neutrophils in response to E. coli infection." (PMID 32587248, 2020).
leukemia (1 paper, 2023). A malignant (clonal) hematologic disorder, involving hematopoietic stem cells and characterized by the presence of primitive or atypical myeloid or lymphoid cells in the bone marrow and the blood. "The feline sarcoma oncogene (FES) is a nonreceptor tyrosine kinase previously associated with leukemia and hematopoietic homeostasis." (PMID 36969004, 2023).
lung adenocarcinoma (1 paper, 2014). A carcinoma that arises from the lung and is characterized by the presence of malignant glandular epithelial cells. "Such mutation was never found for any other cancer types, even among esophageal and lung adenocarcinomas, known for FES mutations." (PMID 24667986, 2014).
malaria (1 paper, 2021). Malaria is a serious and sometimes fatal disease caused by a parasite that commonly infects a certain type of mosquito which feeds on humans. "Our data support a model in which the reducing power from the Fd/FNR system to certain downstream FeS proteins is essential for the survival of blood-stage malaria parasites but not for organelle maintenance, while other FeS proteins are dispensable for this stage of parasite development." (PMID 35164549, 2021).
melanoma (1 paper, 2022). A malignant, usually aggressive tumor composed of atypical, neoplastic melanocytes. "Within the melanoma sequence data, we confirmed exon skipping in three genes–MAP3K3 (exon 3), FES (exon 11) and SLK (exon 13)." (PMID 35560144, 2022). "FES has been previously identified as a tumor suppressor in melanoma, but we did not observe significant DE in our analysis." (PMID 35560144, 2022).
metastatic tumor (1 paper, 2023). "We have previously shown that inhibiting the FES kinase results in a significant reduction in neutrophils at both the primary tumor and the metastatic tumor sites." (PMID 36969004, 2023). "Thus, we analyzed livers of WT and FES KO mice with metastatic disease using flow cytometry to detect any changes in the immune cell composition." (PMID 36969004, 2023). "Our data suggested Lorlatinib inhibited the nonreceptor tyrosine kinase FES in neutrophils resulting in a reduced primary and metastatic tumor burden." (PMID 36969004, 2023).
osteosarcoma (1 paper, 2020). A usually aggressive malignant bone-forming mesenchymal neoplasm, predominantly affecting adolescents and young adults. "This study aimed to screen osteosarcoma (OS) prognosis relevant genes for methylation dysregulation, and the functional mechanisms of FES overexpression in OS cells were investigated." (PMID 32256211, 2020).
renal carcinoma (1 paper, 2020). A carcinoma arising from the epithelium of the renal parenchyma or the renal pelvis. "In addition, downregulated FES can inhibit the proliferation of renal carcinoma cells." (PMID 32256211, 2020).
triple-negative breast carcinoma (1 paper, 2021). An invasive breast carcinoma which is negative for expression of estrogen receptor (ER), progesterone receptor (PR), and human epidermal growth factor receptor 2 (HER2). "Overexpression of CHI3L2 and FES was observed in triple negative breast cancers (TNBCs) relative to other subtypes in immune‐rich tumors." (PMID 34189853, 2021).